INS (insulin)
Diseases named in the same sentence as INS in open-access papers (continued):
Sharing a sentence is not in itself a finding about the gene and the disease.
Obesity (continued). "As adiponectin has insulin-sensitizing properties, IL-6 receptor blockade in combination with exercise training may improve adipocyte function, thereby reducing the risk of developing obesity-associated glucose intolerance." (PMID 33572989, 2021). "Downregulation of lipogenic genes upon HFD feeding or in obesity is associated with the development of adipocyte insulin resistance and thus the upregulation of these genes in the Rptorob−/− mice is likely a secondary effect of their ability to retain sensitivity to insulin." (PMID 33551450, 2021). "Several studies suggest that insulin resistance and cardiovascular disease are linked through ER stress in pathologies like obesity; elevated concentrations of saturated fatty acids could impair vasodilatory action of insulin through ER stress in obese individuals." (PMID 33800427, 2021). "A precise and delineated description of endogenous oxytocin involvement in human insulin secretion, lipid metabolism, thermogenesis, and musculoskeletal function is crucially needed to form an in-depth understanding of the potential effects of oxytocin treatment on obesity-associated co-morbidities." (PMID 34299356, 2021). "In a previous paper, aimed to evaluate the association of circulating miRNAs with obesity in a sample of normal weight (NW) and overweight/obese (OW/Ob) children, we found that hsa-miR-191-3p was associated with obesity and also with markers of insulin sensitivity." (PMID 34243726, 2021). "Therefore, it is speculated that the positive energy balance associated with the development of obesity is the result of an insulin-driven shift toward fat storage and a decrease in fat oxidation due to an increased proportion of dietary CHO." (PMID 33922998, 2021). "Moreover, liquid CHO diets such as the sugar-sweetened beverages are often high in GI; can increase postprandial blood glucose levels, decrease insulin sensitivity and increase the risk of obesity and overweight, which are also important risk factors for the MetS occurrence." (PMID 33731080, 2021). "Thus, insulin signaling in adipocytes is critical for the development of obesity and its associated metabolic abnormalities, and the abrogation of insulin signaling in fat unmasks a heterogeneity in the adipocyte response in terms of gene expression and triglyceride storage." (PMID 34202916, 2021). "Furthermore, VK may reduce the risk for metabolic disorders, such as T2D, by improving insulin sensitivity and anti-inflammatory activity, as well as obesity, through a lipid-lowering effect." (PMID 33917442, 2021). "Even though the causative role of insulin in the development of hypertension is still questioned, the association between IR and hypertension is well documented in pediatrics, and IR is considered the primary pathogenic mechanism underlying MS and a link between obesity and disease." (PMID 34828680, 2021). "Thus, intrauterine programming may be related to the restricted insulin secretory capacity of pancreatic islets as a response to the demands imposed by increased insulin resistance linked to obesity in adult life." (PMID 34276762, 2021). "It is speculated that infants who were introduced to a high quantity of carbohydrates too early in life are more likely to boost insulin secretion with recursive metabolic adaptations, and an increasing susceptibility to elevated weight gain and obesity later on in life." (PMID 34639581, 2021). "Weight loss resulting from consumption of a diet lower in CHO and higher in fat may be beneficial for older adults with obesity by depleting adipose tissue depots most strongly implicated in poor metabolic and functional outcomes and by improving insulin sensitivity and the lipid profile." (PMID 32817749, 2020). "Finally, the activation of purine pathway found in BM of overweight-obese mothers could promote weight gain long after birth, but also improve glucose tolerance and insulin sensitivity in case of obesity, and reduce cardiovascular risk." (PMID 32793208, 2020).
Obesity (continued). "However, the functional consequences of obesity-associated alterations in insulin signaling on the anti-tumor CD8+ T cell response are currently unknown." (PMID 33170123, 2020). "However, the loss of BVRA in obesity can result in hyperactivation of insulin signaling." (PMID 32131495, 2020). "It is yet to be determined whether neuronal resistance to insulin is associated with obesity." (PMID 32272767, 2020). "Therefore, it seems reasonable to speculate that high CRF-related insulin sensitivity may attenuate the individual and synergistic impact of sarcopenia and obesity on the risk of hepatic steatosis." (PMID 32486399, 2020). "In addition to higher visceral and liver fat amounts in insulin resistant obesity, we found insulin sensitive MHO to be associated with less immune cell infiltration into visceral fat depots, lower mean adipocyte size, and a favorable adipokine secretion pattern." (PMID 32128581, 2020). "The obesity-associated gene expression signatures pointed to key metabolic pathways involved in protein synthesis, enhanced cell death from proinflammatory or lipotoxic stimuli, enhanced insulin signaling, and reduced defense control against reactive oxygen species." (PMID 32594318, 2020). "To verify whether overexpression of miR-802 also impairs insulin transcription and secretion in vivo, we mimicked the obesity-associated increase in miR-802 expression in a transgenic mouse model by generating H11-CAG-LSL-miR-802 knock-in mice using CRISPR/Cas9 system." (PMID 32286278, 2020). "Some previous studies suggested that misalignment of circadian rhythm may decrease insulin sensitivity and leptin suppression, and time-restricted feeding is associated with a lower incidence of obesity compared with ad libitum diet with the same caloric intake in mice." (PMID 32948201, 2020). "Obesity has become a burgeoning epidemic in the public health and is inevitably accompanied by the increased level of plasma cholesterol, triglyceride, and blood sugar as well as levels of insulin, which can elevate susceptibility to the cardiovascular diseases." (PMID 32290863, 2020). "This evidence has linked obesity and T2D with altered qualitative and quantitative gut microbiome changes, increased permeability, and ensuing local inflammation in metabolically active remote organs as well as systemic inflammation accounting for an increased systemic insulin resistance." (PMID 32295104, 2020). "Although data regarding dietary intake were not available for the cohorts analysed in our study, we suspect that the high proportion of obesity observed in the suboptimal and high-risk glycaemic control groups may be due to excessive food intake and inappropriate insulin administration." (PMID 33227006, 2020). "The hypothesis that carbohydrate-stimulated insulin secretion is the primary cause of common obesity, and metabolic diseases like T2D, via direct effects on adipocytes, seems difficult to reconcile with current evidence from observational and intervention studies." (PMID 31035514, 2019). "A specific role for pPS-captured defects in insulin secretion and altered gut microbiome has also been reported: those microbiome changes include an effect on butyrate-producing pathways shown to play a causal role with respect to diabetic and obesity phenotypes." (PMID 31322649, 2019). "Moreover, deficiency of leptin secretion or action in mice with obesity and lipodystrophy, respectively, can affect insulin signaling, leading to chronic hyperinsulinaemia associated with hyperglycemia due to a down-regulation of IRS-2, a key mediator of insulin signaling." (PMID 30754657, 2019). "Importantly, previous studies indicate autophagy malfunction in hypothalamic POMC neurons contributes to obesity-associated metabolic dysfunctions, including increased plasma insulin levels, hyperglycemia, glucose intolerance, impaired lipolysis, and leptin resistance." (PMID 30972025, 2019).
Obesity (continued). "Interestingly, it was also suggested that this SOCS1 variant that affects insulin sensitivity early in life may add to the risk of obesity/higher BMI later in life." (PMID 31717271, 2019). "Similarly, differences in circulating leptin and insulin concentrations have been linked to acyclicity in oestrous cycles of horses as a result of obesity, which may be linked to gut microbiome structure." (PMID 30770764, 2019). "Since there were differences in BCS between the two breeds, it could have been interesting to test the horses for insulin regulation, as obesity and insulin dysregulation are important risk factors related to equine metabolic syndrome and endocrinopathic laminitis in horses." (PMID 31878953, 2019). "The modulation of brown adipose tissue activity and browning of white adipose tissue has been proposed as a promising therapeutic strategy in the treatment of obesity-associated metabolic disturbances, with the intention of improving insulin sensitivity and hepatic steatosis, among others." (PMID 30766490, 2019). "The carbohydrate-insulin model (CIM) of obesity hypothesizes that a high-carbohydrate/low-fat diet causes postprandial hyperinsulinemia that promotes fat deposition and decreases circulating metabolic fuels (glucose and lipids), thereby increasing hunger and slowing the whole-body metabolic rate." (PMID 31035514, 2019). "Moreover, although a direct association between breast-feeding and improved insulin sensitivity is unknown, breast-feeding should be promoted because it is involved in preventing obesity in children." (PMID 31214120, 2019). "Therefore, bariatric surgery is an effective treatment for obesity, especially considering the capacity to modulate weight loss, as well as the systemic improvements in insulin responsiveness for the potential treatment of insulin resistance and type 2 diabetes." (PMID 30875990, 2019). "In other words, unbalanced mitochondrial dynamics in the tissues of the pancreas, liver, and muscle, caused by obesity, may increase the production of ROS that induces oxidative stress, which inhibits insulin signaling pathways and ultimately increases insulin resistance leading to diabetes." (PMID 31010272, 2019). "In youth, glucose intolerance is likely to be associated with severe obesity which promotes beta cell hypersecretion of insulin, whereas age-related beta cell decline in BA adults may account for their relatively greater insulin secretory deficits as they progress to T2D." (PMID 31781667, 2019). "Thus, far the impact of obesity per se compared to its associated insulin resistance on the dysregulation of postprandial anabolic response is unknown." (PMID 31263701, 2019). "However, insulin signaling is maintained in bone marrow microenvironment leading to hypermetabolic state of bone marrow stromal (skeletal) stem cells associated with accelerated senescence and accumulation of bone marrow adipocytes in obesity." (PMID 31749085, 2019). "Therefore, the effects of IGFBP-2 on obesity susceptibility and insulin sensitivity are complex and may be influenced by different domains of IGFBP-2 protein." (PMID 30392760, 2019). "Behaviours associated with obesity may also sustain chronic diseases through the induction of pro-inflammatory cytokines and insulin and insulin/IGF-1 resistance—both processes further contributes to the increased production of reactive oxygen species and residual inflammation." (PMID 31426866, 2019). "However, results of several studies showed that other factors, such as higher insulin levels and growth factors, may also increase the risk of endometrial cancer in women with obesity." (PMID 31151429, 2019). "The obesity is usually associated with increased mitochondrial ROS production, causing the oxidized lipids, synthesis of faulty proteins, and mtDNA mutations, which are related to decreased metabolic activity, mitochondrial dysfunction, and cellular insulin sensitivity." (PMID 29695233, 2018).
Obesity (continued). "Thus, loss of proper gap junction coupling and coordinated beta cell responses to secretagogues, may lead to impaired insulin release under conditions associated with T2DM (i.e. obesity, inflammation and gene silencing)." (PMID 29661799, 2018). "For instance, rodents chronically exposed to a high-fat diet develop dyslipidemia, white adipose tissue expansion, insulin resistance, and altered metabolic regulatory hormones constituting a useful tool to evaluate the potential mechanisms underlying the effects of yacon on obesity." (PMID 30510798, 2018). "Interestingly, contrary to African American women maintaining lifetime normal weight, those who were overweight before in their lives were more insulin sensitive and thus might be predisposed for obesity and fat accumulation." (PMID 29780358, 2018). "Obesity-associated cancer may be driven by the high levels of insulin and insulin-related growth factors, the chronic inflammatory environment or in the case of breast and ovarian cancers, by the fact the adipose tissue produces oestrogen, which can stimulate abnormal cell growth." (PMID 30509933, 2018). "Since both insulin and cytokine signaling in the brain regulate synaptic plasticity, learning and memory, neuroinflammation and neuronal insulin resistance may be key mediators of obesity-associated cognitive decline." (PMID 30692905, 2018). "Thus, suggesting that additional studies are required to explore molecular mechanisms involved in the beneficial effect of gallic acid-rich teas against obesity associated complications, especially targeting its role in adipogenesis, insulin signaling, inflammation, and oxidative stress processes." (PMID 30577684, 2018). "Suppression of obesity-associated inflammation in different tissues, including adipose tissue, liver, intestine etc. by different nutritional interventions can operate separately or synergistically to ameliorate systemic insulin sensitivity and metabolic homeostasis." (PMID 30602666, 2018). "The present study investigated whether hippocampal-dependent spatial memory impairments in a dietary induced mouse model of obesity could be improved by the direct administration of insulin into the hippocampus and whether this was associated with markers of hippocampal inflammation." (PMID 30619085, 2018). "Our results indicate that TCPTP status may define POMC neural responses to insulin so that feeding-associated diurnal fluctuations in TCPTP or elevated TCPTP levels in obesity might dictate whether POMC neurons are activated by insulin or are otherwise inhibited or remain unresponsive." (PMID 30230471, 2018). "Furthermore, deficiency of T cells, including CD4+ T cells or IFN-γ significantly reduces adipose tissue inflammation and improves insulin sensitivity in obese mice, suggesting the substantial contribution of Th1 cells to adipose inflammation and metabolic dysfunctions associated with obesity." (PMID 30459770, 2018). "Similarly, increased insulin promotes storage of lipids in adipose tissue; so again a primary hysteretic drive increasing insulin secretion could plausibly be the cause of obesity as well." (PMID 29892261, 2018). "Additionally, these three clusters related to insulin action (Obesity, Lipodystrophy, Liver/Lipid) are enriched for variants overlaying enhancers in tissues that biologically support their proposed mechanisms: pre-adipocytes, adipocytes, and liver tissue, respectively." (PMID 30240442, 2018). "Physical activity been hypothesized to reduce breast cancer risk through several mechanisms, including weight loss, obesity prevention, reduced sex hormone exposure, reduced levels of insulin and insulin-like growth factor exposure, induced immune system function, and mechanism of DNA repair." (PMID 30194548, 2018). "This demonstrates that CNS insulin can improve hippocampal-dependent memory and that hippocampal inflammation may be a factor in the development of cognitive deficits associated with diet-induced obesity." (PMID 30619085, 2018).
Obesity (continued). "Taken together, reallocation from Mpro like towards Manti type ATMs might be a promising strategy to resume whole body insulin sensitivity that would prevent fatal diseases associated with obesity such as development of metabolic syndrome and the progression to cancer." (PMID 28233125, 2017). "The correlation of decreased plasma insulin concentrations and decreased OA-like changes in rats fed LA, and the increased OA-like changes in rats fed PA and SA in our study strongly supports the role of insulin in OA associated with glucose intolerance and obesity." (PMID 28418007, 2017). "Accordingly, metabolic inflexibility in obesity-associated insulin resistant individuals was correlated to reduced intermyofibrillar mitochondrial content, which could not be accounted for by differences in mitochondrion size, muscle fiber distribution, or maximal aerobic capacity." (PMID 29097020, 2017). "The inhibition of the signaling pathway in the gh–ghr–igf axis led to decreased serum Gh levels that may affect insulin secretion, and caused over up-regulation of lipid metabolism in the fat cells resulting in obesity or promoting gluconeogenesis resulting in elevated blood glucose levels." (PMID 29270127, 2017). "The study was also limited by the lack of information on other biological makers, such as serum triglycerides, C-reactive protein, glucose, insulin, and cholesterol, which could have provided an input to the interpretation of the associations between FAs and obesity." (PMID 28465289, 2017). "Leptin deficiency leads to obesity and concomitant hormonal changes that might exert a neurotrophic effect on brainstem circuits, e.g., increased levels of amylin and insulin, that may perhaps compensate over time for the lack of leptin’s neurotrophic action in ob/ob while the animals gain weight." (PMID 29250032, 2017). "Weight-adjusted lean body mass was protective against obesity-associated metabolic abnormalities; it negatively correlated with systolic and diastolic blood pressures and fasting plasma glucose, HbA1c, alanine aminotransferase, TG and insulin levels and positively correlated with HDL-C levels." (PMID 28721400, 2017). "Indeed, a number of mechanistic studies demonstrated that acute pharmacologic ganglionic blockade by trimetaphan is able to reduce blood pressure, to improve insulin sensitivity and to reverse endothelial function in obesity, in particular if associated with hypertension." (PMID 28966594, 2017). "As reduced dopamine function has been implicated in compulsive behaviors and reduced energy expenditure and insulin dysregulation incurs increased obesity risk, changes in glucose regulation and dopamine function induced by HFCS may precede and contribute to obesity in the long-run." (PMID 29287121, 2017). "In addition, elevated insulin levels have been suggested to be a causal factor for obesity." (PMID 29038790, 2017). "One hypothesis that would be in line with our results is that obesity leads to increasing insulin levels and risk of hyperinsulinemia, which in turns decreases insulin-like growth factor (IGF) binding proteins, thus allowing increasing circulating levels of insulin-like growth factor I (IGF1)." (PMID 28954281, 2017). "Consequently, these data together with the mitochondrial respiratory profile suggest that resistance to obesity and better insulin sensitivity induced by Mfn2 deletion in BAT is linked to increased coupled fatty acid oxidation in BAT and, possibly, in other tissues." (PMID 28539390, 2017). "Obesity is associated with increased circulating levels of insulin and insulin-like growth factor as well as excess production of estrogens in adipose tissue, both of which may promote meningioma development, especially in obese women, to whom the positive risk association was limited in our study." (PMID 27903988, 2017). "This may also be mainly associated with obesity-induced inflammation and insulin sensitivity." (PMID 28466023, 2017).